GFPT2 (glutamine--fructose-6-phosphate transaminase 2)
Diseases named in the same sentence as GFPT2 in open-access papers (continued):
Sharing a sentence is not in itself a finding about the gene and the disease.
tumor (continued). "Notably, GFPT2 and NF-κB form a positive feedback loop by mutually enhancing each other to promote tumor development." (PMID 40830088, 2025). "Furthermore, glutamine depletion by tumor cells overexpressing glutamine-fructose-6-phosphate transaminase 2 (GFPT2) inhibits mitochondrial fission-mediated cytosolic calcium in macrophages." (PMID 39905317, 2025). "Additionally, increased expression of GFPT2 promotes acylation of p65 to o-glcnac, and accelerates nuclear translocation of p65, thereby enhancing NF-κB activity and promoting tumor progression." (PMID 39834822, 2024). "The results showed that GFPT2 knockdown significantly inhibited tumor growth in nude mice." (PMID 38575607, 2024). "GFPT2 overexpression significantly promoted tumor growth in nude mice." (PMID 38575607, 2024). "In parallel, the scRNA data from 15 PDAC tissues samples also showed higher infiltration of cells expressing SMC/fibroblast markers (PDPN, COL5A1, COL22A1, TIMP3, SPARC, WT1, GFPT2) in samples with higher proportions/fractions of MUC16-expressing tumor (epithelial) cells (n = 7)." (PMID 36816942, 2023). "Additionally, they demonstrated that selectively inhibiting the HBP enzyme GFPT2 led to reduced growth of KRAS/LKB1 co-mutant tumor cells in culture, xenografts, and genetically modified mice." (PMID 37880766, 2023). "GFPT2+CAFs positively correlates with immunosuppressive cells and T-cell exhaustion, implying that GFPT2 may be involved in immune escape of tumor cells." (PMID 37143134, 2023). "Inhibiting glycosylation by inhibiting glutamine-fructose-6-phosphate transaminase 2 (GFPT2) causes cell death in KL tumor cells but not in KRASG12D tumor cells." (PMID 35573694, 2022). "To examine the status of the HBP in human NSCLC, we assessed the expression level of its rate-limiting enzyme paralogs GFPT1 and GFPT2 using publicly available gene expression data of paired tumor-normal samples (LUAD n = 58; LUSC n = 52) from The Cancer Genome Atlas (TCGA)." (PMID 35396334, 2022). "In order to validate expression of c-Myc on the protein level in subtype 2 of LMS, we performed IHC with a monoclonal antibody against c-Myc on 58 of the 59 tumor specimens that had been used for the transcriptomic analysis and GFPT2 protein expression analysis." (PMID 33941787, 2021). "In order to validate overexpression of GFPT2 on the protein level in one of the molecular subtypes of LMS, we performed immunohistochemistry (IHC) with a monoclonal antibody against GFPT2 on 59 of the 70 tumor specimens that had been used for the transcriptomic analysis." (PMID 33941787, 2021). "While the NSCLC tumors that displayed the highest GFPT2 score indexes were associated with late-stage tumors, the degree of GFPT2 staining by IHC did not correlated with tumor stage in any of the subtypes examined." (PMID 30885209, 2019). "In addition to being expressed in CAFs, GFPT2 is also expressed in tumor parenchymal cells." (PMID 37143134, 2023). "In addition, GFPT2 expression was correlated with the tumor microenvironment (TME)." (PMID 35330716, 2022). "Conversely, we observed a significant downregulation of tumor-suppressive transcriptional regulators such as CPEB1, CDH15, GFPT2, and PLA2G2A." (PMID 40950184, 2025). "Comparative analyses of GFPT isoform expression across diverse tumor types reveal that GFPT1 is broadly and constitutively expressed, while GFPT2 exhibits more restricted, tumor-specific expression patterns." (PMID 40830088, 2025). "Therefore, GFPT2 may be involved in tumor cell immune escape." (PMID 35330716, 2022). "To explore whether targeting the GFPT2- O-GlcNAcylation signal axis has potential clinical significance, we used KPC cells to construct the subcutaneous implant tumor model in C57BL/6 mice, and OSIM-1 was injected intraperitoneally every other day." (PMID 38575607, 2024).
tumor (continued). "We have known that GFPT2 expression related to ECM and immune pathways, since stromal cells and immune cells are major components of the tumor microenvironment (TME), so we speculated whether GFBP2 would be involved in TME." (PMID 35330716, 2022). "While GFPT2 protein levels did not necessarily track with tumor-stage, GFPT2 expression was elevated in all subtypes of NSCLC with the highest incidence found in LUAD and LULC tumors (69 and 58%, respectively)." (PMID 30885209, 2019). "Indeed, inhibition of either GFPT2 (glutamine-fructose-6-phosphate transaminase 2), a central enzyme of the hexosamine pathway, or the acetyl-coA carboxylase (ACAC, key for fatty acid synthesis), blocks NSCLC tumor growth." (PMID 37370686, 2023). "Similarly, another independent GSE3167 dataset also displayed the increased mRNA expression levels of GFPT1, PGM3, and UAP1 and the decreased GFPT2 level in tumor tissues, while the data of GNPNAT1 gene were not available in this dataset." (PMID 36158580, 2022).
infection (3 papers, 2020 to 2024). The state of being infected such as from the introduction of a foreign agent such as serum, vaccine, antigenic substance or organism. "The recovered pigs had a significant down-regulation of HTRA3 and GFPT2 of up to 12.85 and 9.57 fold, respectively, before the infection challenge compared to recovered pigs." (PMID 38467747, 2024).
digestive system tumors (1 paper, 2022). "GFPT2 in the study was also closely related to the prognosis, microenvironment, immunity, and drug sensitivity of other digestive system tumors, and the specific internal mechanism remained to be further studied." (PMID 36276279, 2022).
GFPT2 also shares sentences with these, for which no sentence is quoted: cardiac hypertrophy (3 papers); glioblastoma (2); breast tumor (1); diabetic nephropathy (1); diabetic retinopathy (1); Gaucher disease (1); Impaired glucose tolerance (1); ischemia (1); liver fibrosis (1); mesenchymal tumors (1); mesothelioma (1); metabolic syndrome (1); metabolism disorder (1); myocardial infarction (1); Obesity (1); pancreatic ductal adenocarcinoma (1); renal cell carcinoma (1); sarcoma (1); schizophrenia (1); triple-negative breast carcinoma (1).